Y_RNA (Y RNA )
Gene: Miscellaneous RNA gene on chromosome 16 (68,089,449 to 68,089,543, reverse strand). Ensembl gene ENSG00000201850.
Homologues: Orthologues: chimpanzee Y_RNA (98% identical). Paralogues in human: Y_RNA (88% identical), RNY4P14 (85% identical), RNY4 (84% identical), RNY4P10 (83% identical), RNY4P24 (82% identical), RNY4P7 (82% identical), RNY4P3 (81% identical), RNY4P6 (81% identical), Y_RNA (81% identical), RNY4P17 (80% identical), RNY4P25 (80% identical), Y_RNA (80% identical), and 92 more.